MMP10 (matrix metallopeptidase 10)
Diseases named in the same sentence as MMP10 in open-access papers (continued):
Sharing a sentence is not in itself a finding about the gene and the disease.
gastric cancer (6 papers, 2012 to 2023). A primary or metastatic malignant neoplasm involving the stomach. "Therefore, MMP-7 and MMP-10 may be important MMPs in gastric cell invasion during H. pylori-associated gastric cancer development." (PMID 36014933, 2022). "This study supports the present finding showing that dietary β-carotene, which is abundant in fruits and vegetables, may reduce H. pylori-associated gastric cancer incidence by reducing the oxidative stress-mediated MMP-10 expression and invasive property of gastric epithelial cells." (PMID 33809289, 2021). "H. pylori infection increases the expression and secretion of various MMPs, including MMP-1, MMP-9, MMP-7, and MMP-10, in the gastric epithelial cells or gastric cancer cells." (PMID 33809289, 2021). "MMP-1 and MMP-10 expression in patients with gastric cancer and in those with metastatic gastric cancer was significantly higher than that in patients with gastritis." (PMID 25120597, 2014). "The MMP-10-positive rate in the patients with gastric cancer, metastatic gastric cancer and chronic gastritis was 83.4% (67/80), 95.0% (19/20) and 30.0% (12/40), respectively." (PMID 25120597, 2014). "Statistically, the expression levels of MMP-1 and MMP-10 were significantly higher in the gastric cancer specimens than those in the chronic gastritis specimens (P<0.05)." (PMID 25120597, 2014). "In this study, in order to determine the effect of H. pylori infection on gastric cancer, the associations among H. pylori infection, the expression of MMP-1 and MMP-10 and the invasion and metastasis of gastric cancer were investigated." (PMID 25120597, 2014). "H. pylori infection and MMP-1 and MMP-10 expression were detected in gastric cancer and chronic gastritis specimens." (PMID 25120597, 2014). "As signaling pathways for MMP expression, H. pylori infection induces MMP-1 expression via c-Jun N-terminal kinase (JNK) and extracellular-signal-regulated kinase (ERK) pathways in gastric cancer cells and MMP-10 expression via the ERK pathway in gastric epithelial cells." (PMID 33809289, 2021). "However, positive staining for MMP-1 and MMP-10 was detected in the poorly and moderately differentiated gastric cancer and gastric cancer with lymph node metastasis specimens." (PMID 25120597, 2014). "The positive expression of MMP-1 and MMP-10 was associated with lymph node metastasis and clinical stage, but not with age, gender or differentiation degree, indicating that MMP-1 and MMP-10 expression was involved in gastric cancer metastasis." (PMID 25120597, 2014). "It was also found that MMP-1 expression was correlated with MMP-10 expression, indicating that these two different types of MMPs may play a synergic role in gastric cancer genesis, invasion and metastasis." (PMID 25120597, 2014). "In this study, the results indicate that in the H. pylori-induced MMP secretion in gastric cancer cells, MMP-10 may be involved in the activation of MMP-1." (PMID 25120597, 2014). "Thus, the simultaneous detection of MMP-1 and MMP-10 may be important in the evaluation of the prognosis and metastasis of gastric cancer." (PMID 25120597, 2014). "It was revealed that MMP-1 and MMP-10 expression was significantly positively correlated in gastric cancer (r=0.8321, P<0.05; data not shown)." (PMID 25120597, 2014). "This study has shown that MMP-1 and MMP-10 expression was higher in patients with gastric cancer with metastasis than in those with gastric cancer without metastasis." (PMID 25120597, 2014). "H. pylori infection may be involved in gastric cancer metastasis through the mechanism of upregulating the expression of MMP-1 and MMP-10." (PMID 25120597, 2014). "Furthermore, compared with levels in the gastric cancer specimens, the expression levels of MMP-1 and MMP-10 in the metastatic gastric cancer specimens were significantly higher (P<0.05)." (PMID 25120597, 2014).
gastric cancer (continued). "H. pylori infection may promote the invasion and metastasis of gastric cancer by increasing the expression of MMP-1 and MMP-10." (PMID 25120597, 2014). "Finally, great of relevance, we found an upregulation of Matrix Metalloproteinase family (MMP1, MMP3, MMP10, MMP12), that are overexpressed in gastric cancer as a result of NF-Kb activation thus promoting migration and invasion, and are associated with poor prognosis." (PMID 34012923, 2021).
osteoarthritis (6 papers, 2020 to 2024). A noninflammatory degenerative joint disease occurring chiefly in older persons, characterized by degeneration of the articular cartilage, hypertrophy of bone at the margins and changes in the synovial membrane. "For example, WISP-3 overexpression in normal cartilage (C-28/I2) cells dramatically reduces the expression of ADAMTS-4 and ADAMTS-5, and markedly elevates matrix metalloproteinase-1 (MMP-1) and MMP-10 expression, leading to the degradation of cartilage and the development of osteoarthritis." (PMID 34680447, 2021). "MMP-10, named as stromelysin-2, also increases in early- and end-stage osteoarthritis." (PMID 32189997, 2020). "The genes enriched in the osteoarthritis pathway revealed by IPA of the DEGs in the palovarotene-treated chondrocytes included various matrix catabolic genes (Adamts4, Adamts5, Mmp9, Mmp10, Mmp12, and Mmp13) and cell death-related genes (Casp1, Casp3, and Casp6)." (PMID 39062860, 2024).
prostate carcinoma (6 papers, 2005 to 2024). A carcinoma that arises from epithelial cells of the prostate gland. "While investigating the extracellular function of MMPs in ECM remodeling, we observed prominent nuclear immunostaining for MMP-3 and MMP-10 in the cancerous lesions of prostate cancer." (PMID 28831065, 2017). "This was also the case for MMP10, which likewise showed elevated expression in prostate cancer epithelium." (PMID 15928670, 2005). "Collectively, these clinical observations indicate that MMP-3 alone—and not both MMP-3 and MMP-10—exhibits opposite expression patterns in stromal fibroblasts and prostate cancer cells and an overall increase in MMP-3 in patient sera." (PMID 28831065, 2017). "By contrast, there was no statistical significance in the serum MMP-10 concentration between BPH (484.7 ± 157.7 pg/ml) and prostate cancer patients with either low-grade tumors (810.7 ± 552.2 pg/ml) or high-grade tumors (1069.3 ± 1197.3 pg/ml)." (PMID 28831065, 2017).
tongue cancer (6 papers, 2011 to 2024). A malignant neoplasm affecting the tongue. "We also show that miR-944 negatively regulates MMP10, and AXL signaling pathway mediates phenotypes associated with MMP10 overexpressing tongue cancer." (PMID 36650344, 2023). "We previously reported over-expression of MMP10 and its association with nodal metastases in early tongue cancer patients." (PMID 36650344, 2023). "We demonstrate that proliferation, migration, and invasion of tongue cancer cells are suppressed by MMP10 knockdown or miR-944 overexpression." (PMID 36650344, 2023). "Lastly, we validate our in vitro findings establishing the role of MMP10 in tongue cancer metastasis using an orthotopic tongue tumor mouse model." (PMID 36650344, 2023). "Overall, we observed significant downregulation of miR-944 and upregulation of MMP10 in tongue cancer patients with nodal metastasis, suggesting that miR-944/MMP10 is potentially involved in regulating lymph node metastasis." (PMID 36650344, 2023). "Taken together, these findings indicate that MMP10-mediated migration and invasion of tongue cancer cells is regulated by activation of the AXL signaling pathway and upregulation of EMT marker genes." (PMID 36650344, 2023). "Further, we show that depletion of MMP10 prevents nodal metastases using an orthotopic tongue cancer mice model." (PMID 36650344, 2023). "Taken together, these results reveal that miR-944 is a negative regulator MMP10 and suppresses the metastatic phenotype of tongue cancer cells upon its upregulation." (PMID 36650344, 2023). "IHC results suggest significant overexpression of MMP10 protein in tongue cancer patients with lymph node metastasis (p = 0.0035)." (PMID 36650344, 2023). "To confirm the in vitro findings and study the role of MMP10 in tumorigenesis and metastasis of tongue cancer in vivo, we established orthotopic tongue tumor mouse model using the MMP10 overexpression and knockdown clones." (PMID 36650344, 2023). "The inhibition of MMP10 notably diminishes the viability of tongue cancer cells with DDX5 knockdown, suggesting that MMP10 is one of the key genes confronting the DDX5-mediated inhibition of tongue cancer cell proliferation." (PMID 38136426, 2023). "Transcriptome sequencing was performed to investigate MMP10 downstream targets involved in the regulation of tongue cancer metastasis." (PMID 36650344, 2023). "Secondly, ectopic overexpression or shRNA-mediated knockdown of MMP10 affects cell proliferation, migration, and invasion of tongue cancer cells." (PMID 36650344, 2023). "Remarkably, our research reveals that DDX5 counteracts the expression of genes pivotal to tongue cancer progression, such as MMP10." (PMID 38136426, 2023). "To investigate the role of MMP10 in metastasis of tongue cancer, we screened for MMP10 expression in three tongue cancer cell lines (AW13516, AW8507, and CAL27) by quantitative real-time PCR and Western blotting." (PMID 36650344, 2023). "And, overexpression of AXL promotes MMP10-suppressed proliferation, invasion, and migration of tongue cancer cells." (PMID 36650344, 2023). "In conclusion, our results establish that the miR-944/MMP10/AXL- axis underlies lymph node metastases with potential therapeutic intervention and prediction of nodal metastases in tongue cancer patients." (PMID 36650344, 2023). "In a reciprocal approach, to study if MMP10 expression is essential for the metastatic properties of tongue cancer cells, shRNA-mediated knockdown of MMP10 was performed in AW8507 and CAL27 cells." (PMID 36650344, 2023). "Overall, we observed significant upregulation of MMP10 in tongue cancer patients with nodal metastasis, across 208 in-house and 112 TCGA tongue cancer samples." (PMID 36650344, 2023). "Taken together, these results suggest that upregulation of MMP10 is sufficient and essential to promote migration and invasion of tongue cancer cells." (PMID 36650344, 2023).
tongue cancer (continued). "Here, we present the molecular mechanism of miR-944/MMP10/AXL- axis mediated tongue cancer metastasis." (PMID 36650344, 2023). "Similar correlation is also observed in abundance of Fusobacterium and expression of MMP10 in tongue cancer, a biomarker of lymph node metastases mechanistically shown to be driving invasion and migration in tongue cancer." (PMID 37322598, 2023). "In overall, we present the first descriptive portrait of somatic alterations underlying the genome of tobacco/nut chewing HPV-negative early tongue cancer, and identify MMP10 as a potential prognostic biomarker to stratify those likely to develop metastases." (PMID 28939077, 2017). "Interestingly, knockdown of MMP10 significantly reduced the tumor volume in both AW8507-induced and CAL27-induced compared to the control group, suggesting the role of MMP10 in tumorigenesis of tongue cancer." (PMID 36650344, 2023). "Furthermore, we correlated MMP10 transcript expression with nodal metastases in the TCGA-tongue cancer data of early stage as well as early and advanced stage samples." (PMID 36650344, 2023). "The findings suggest MMP10 is strongly correlated with nodal metastases in tongue cancer." (PMID 36650344, 2023). "We set to study the role of AXL in MMP10-promoted invasion and migration of tongue cancer." (PMID 36650344, 2023). "Furthermore, ectopic expression of miR-944 or knockdown of AXL suppresses MMP10-promoted proliferation, invasion, and migration of tongue cancer cells, indicating a therapeutic approach to target tongue cancer." (PMID 36650344, 2023). "Moreover, we show that overexpression of miR-944 downregulates MMP10, thereby, suppressing proliferation, migration, and invasion of tongue cancer cells." (PMID 36650344, 2023). "MMP10, which is upregulated in 86% of primary tongue tumors with lymph node metastases, is negatively regulated by miR-944 and promotes nodal metastasis in an orthotopic tongue cancer mouse model through the AXL signaling pathway." (PMID 36650344, 2023). "However, the role of MMP10 remains unexplored in lymph node metastasis in early stage tongue cancer." (PMID 36650344, 2023). "Interestingly, knockdown of AXL suppresses MMP10-promoted proliferation, invasion, and migration of tongue cancer cells." (PMID 36650344, 2023). "Interestingly, MMP-10 is also upregulated in tongue cancer by comparing genome-wide transcriptomic profiles between 53 primary tongue cancer and 22 matching normal tissues." (PMID 21998657, 2011). "Notably, the knockdown of MMP10 considerably curtailed the viability of DDX5-KD tongue cancer cells, suggesting MMP10 as a pivotal gene that counteracts the DDX5-associated inhibition of tongue cancer cell proliferation." (PMID 38136426, 2023). "Thus, low expression of miR-944 or overexpression of MMP10 as a prognostic biomarker could also help predict nodal metastasis in tongue cancer, an assessment that awaits designing a larger prospective randomized clinical trial." (PMID 36650344, 2023). "To validate if MMP10 expression could stratify tongue cancer patients likely to develop metastases, we performed immunohistochemistry (IHC) for MMP10 protein using 98 retrospectively collected clinical samples that were part of the phase-3 N-zero clinical trial (NCT00193765)." (PMID 36650344, 2023). "Furthermore, an integrated gene-expression analysis of 253 tongue tumors suggested an upregulation of metastases-related pathways and over-expression of MMP10 in 48% tumors that may be crucial to predict nodal metastases in early tongue cancer patients." (PMID 28939077, 2017). "Next, to understand the role of miR-944 in metastasis of tongue cancer, miR-944 was transiently overexpressed in AW8507 cells, which has endogenously low expression of the miR-944 and high expression of MMP10." (PMID 36650344, 2023).
tongue cancer (continued). "In the current study, we validate MMP10 expression in a large cohort of tongue patient samples with nodal metastases and describe the mechanistic role of miR944/MMP10/AXL- axis in tongue cancer using in vitro biochemical and cell-based assays and in vivo orthotopic tongue tumor mouse model." (PMID 36650344, 2023).
cognitive decline (5 papers, 2022 to 2026). "MMP-10 levels are linked to age at onset and cognitive decline." (PMID 42020929, 2026). "Notably, in our cohort the association of MMP-10 levels with functional and cognitive decline was female-specific, and we also found a female-specific effect of age on MMP-10 levels." (PMID 37221606, 2023). "Mild cognitive impairment individuals with elevated cerebrospinal fluid levels of MMP-10 had a higher likelihood of progression to Alzheimer’s type dementia and faster cognitive decline." (PMID 38742104, 2024). "Furthermore, sex-stratified analyses suggest that higher baseline MMP-10 levels might be associated with faster functional and cognitive decline in women, but not in men." (PMID 37221606, 2023). "In patients with MCI due to AD, but not cognitively stable MCI, elevated MMP-10 was accompanied by increased levels of other inflammatory proteins, suggesting that acceleration of cognitive decline is likely due to the cumulative effect of different pathological processes." (PMID 36031900, 2022).
COVID-19 (5 papers, 2021 to 2023). A disease caused by infection with severe acute respiratory syndrome coronavirus 2. "CCL23, among the other seven proteins (IL-17C, MMP-10, FGF-19, FGF-21, FGF-23, and CXCL5), was higher in asymptomatic COVID-19 patients than in patients with symptoms." (PMID 37834869, 2023). "Our study showed a consistent upregulation of MMPs (MMP1, MMP7, MMP10, and MMP12) in post-COVID-19 individuals, suggesting ongoing remodeling processes in individuals that experienced mild disease." (PMID 36405747, 2022). "Importantly, IL-17C, MMP-10, FGF-23 and CCL23 are upregulated only in asymptomatic participants early after infection, which strongly suggests their role in the control of COVID-19 clinical signs." (PMID 35479098, 2022).
emphysema (5 papers, 2016 to 2025). "First, smokers and patients with emphysema have increased concentrations of MMP-10 in blood and bronchoalveolar lavage samples." (PMID 40343765, 2025). "In addition, several lines of evidence implicate MMP-10 in the development of the pulmonary comorbidity emphysema." (PMID 40343765, 2025). "Similarly, Mmp10 has been implicated in pulmonary inflammation and the development of pathologies such as emphysema and chronic obstructive pulmonary disease, with high levels of MMP10 expression noted in the lungs of rats under hypoxic stress." (PMID 38203705, 2023). "DiffCoEx analysis showed that four hub genes (IFT88, CCDC103, MMP10 and Bik) were consistently expressed in emphysema patients; these hub genes were enriched, respectively, for functions of cilium assembly and movement, proteolysis and apoptotic mitochondrial changes." (PMID 31419013, 2019). "Furthermore, all emphysema sub-types, apart from mild CLE, had associations with multiple MMPs, particularly the stromelysins MMP-3 and MMP-10, implicating these proteases in the tissue destruction that occurs in these sub-types of emphysema." (PMID 27460105, 2016). "Second, mice lacking the MMP10 gene fail to develop emphysema even after 6 months of chronic exposure to cigarette smoke." (PMID 40343765, 2025).
glioma (5 papers, 2005 to 2024). A benign or malignant brain and spinal cord tumor that arises from glial cells (astrocytes, oligodendrocytes, ependymal cells). "A biostatistical analysis of data from 276 histologically confirmed gliomas found that a high level of MMP3 expression and a low level of MMP10 were directly related to worse survival." (PMID 38474106, 2024). "In agreement with our sequencing results, three of the five lncRNAs (TCONS_l2_00004574, uc031tga.1, and uc022adp.1) and four of the five mRNAs (NPTX2, HIST2H3C, MMP10, and HIST1H1B) were found to be differentially expressed in the glioma samples (P < 0.05)." (PMID 32211318, 2020).
Hypertension (5 papers, 2020 to 2025). The presence of chronic increased pressure in the systemic arterial system. "There is a study suggesting that MMP-10 might be involved in the development of hypertensive nephropathy once essential hypertension has been established, since circulating MMP-10 is elevated in ESRD patients, when compared with normotensive and hypertensive groups." (PMID 35216251, 2022).